SIRT1 (sirtuin 1)
Diseases named in the same sentence as SIRT1 in open-access papers (continued):
Sharing a sentence is not in itself a finding about the gene and the disease.
tumor (continued). "Consistent with the in vitro findings, suppressing both AMPK and FOXO3 in SIRT1-overexpressing xenograft tumors substantially reversed the improved cisplatin sensitivity, as indicated by the tumor volumes and TUNEL staining." (PMID 32051395, 2020). "HIF-1 has the effects of hypoxia adaptation, inflammation development and tumor growth, and SIRT1 can affect apoptosis by regulating HIF-1α." (PMID 32347300, 2020). "It was found that resveratrol exerts these anti-tumor impacts by affecting mitochondrial respiration through Sirt1 up-regulation." (PMID 32163546, 2020). "It acts as a tumor suppressor by targeting the oncogene SirT1 in endothelial cells or act as an oncogene by targeting PTEN in kidney cells." (PMID 33344459, 2020). "To further validate the correlation between SIRT1 expression and tumorigenesis, we examined the transcript abundance of tumorigenic signatures in TCGA tumor patients." (PMID 32276460, 2020). "GSEA data revealed that a set of upregulated genes during tumorigenesis was markedly reduced in the SIRT1-high group, implying SIRT1 as a tumor suppressor (left)." (PMID 32276460, 2020). "In contrast to the tumor-suppressing role of SIRT1, the role of shikonin involves promoting liver cancer cell death by downregulating the SIRT1-MDR1/P-gp signaling pathway." (PMID 31956359, 2020). "In order to explore the function of Sirt1 in DLBCL chemoresistance, nude mice were used to establish tumor-models to assess the drug-resistance effect of Sirt1 in DLCBL." (PMID 32570218, 2020). "Taken together, these results suggest that SIRT1 would act as a tumor suppressor by modulating RAS-driven ERK activity through MKP1 deacetylation." (PMID 32276460, 2020). "This is due to the controversy of published articles that reported SIRT1 regulates different transcriptional factors acting as a tumor suppressor and/or a tumor promoter protein." (PMID 32607257, 2020). "Even though the role of SIRT1 in metabolism and life span is generally well defined, its activity in malignancy is complex, and either SIRT1 serves as a tumor silencer or a tumor promoter is even now a subject with level-headed discussion." (PMID 32607257, 2020). "In 9L tumors, increased levels of SIRT1 expression were observed in tumor cells surrounding cavernous vessels and in the pseudopalisading zones." (PMID 32118205, 2020). "We identified that SIRT1 is elevated in HBV-related HCC patients with metastasis by detected the expression of SIRT1 in tumor tissues from the patients." (PMID 32714081, 2020). "The role of Situin 1 (SIRT1) in tumorigenesis is still controversial due to its wide range of substrates, including both oncoproteins and tumor suppressors." (PMID 32276460, 2020). "We found that TOX and potentially TIM-3, CTLA-4, VISTA, TIGIT, KLRG1, TOX2, SIRT1, Ki-67, and Helios mRNA levels in tumor tissue were elevated in advanced disease stages, suggesting their potential roles in CRC progression." (PMID 32393998, 2020). "In this study, we evaluated and correlated the SIRT1 expression with patients’ tumor characteristics in endometrioid and clear-cell cancer of the uterus." (PMID 32388637, 2020). "Recently, AMPK activated by SIRT1 is proven to act as a tumor suppressor in multiple solid tumors by inducing cell death, inhibiting cell migration, and attenuating hypoxia-induced chemoresistance." (PMID 32051395, 2020). "With this coordination, SIRT1 promotes tumor cell survival and growth through the deacetylation and inactivation of PTEN, then indirectly activates the PI3K/AKT pathway." (PMID 32607257, 2020).
tumor (continued). "SIRT1 also acts as a tumor suppressor via the c-Myc-SIRT1 feedback loop that regulates cell growth and transformation." (PMID 31956359, 2020). "The miRNA-34 inhibits the proliferation of breast cancer cells through a mechanism of SIRT1 and Bcl-2 downregulation, and thus miR-34 seems to have an anti-tumor effect." (PMID 33123088, 2020). "SIRT1 can also deacetylate Ku70 in tumor and retinal cells to enhance DNA repair activity and chelate Bcl-2-associated X protein (Bax) in the cytoplasm to prevent apoptosis and extend cell lifespan." (PMID 33269110, 2020). "Direct and indirect approaches showed a dual relationship between melatonin and SIRT1 in normal and tumor cells." (PMID 33042011, 2020). "For example, two studies came to different conclusions regarding the in vivo influence of SIRT1 on tumor biology." (PMID 33330467, 2020). "First, nude mice were subcutaneously inoculated with either LY-10/Vector1 and LY-10/Sirt1 or LY-10/Vector2 and LY-10/Si-Sirt1, and then treated with Adriamycin, twice per week, as soon as the tumor became palpable." (PMID 32570218, 2020). "In vivo evidence from mouse xenografts injected with the double knockdown cells revealed that the ablation of SIRT1 expression counteracted the effects of SIRT4 decline on tumor growth, which is consistent with the IHC data of Ki67 staining." (PMID 32863939, 2020). "Immunofluorescence staining (IF) in 9L tumors for SIRT1 demonstrated that the enzyme is overexpressed in the tumor parenchyma in a heterogeneous pattern." (PMID 32118205, 2020). "Results showed that SIRT1, 2, and 4 were up-regulated in tumor tissues while SIRT3 and 5 displayed decreased expression levels." (PMID 33093847, 2020). "SIRT1 also interferes with glycolysis in tumor cells by activating HIF-2α, thereby regulating energy metabolism in tumors." (PMID 33585187, 2020). "Multiple foci of SIRT1 over-expression were dispersed throughout the i.c. tumor parenchyma, demonstrating tumor cell subpopulations responding to hypoxia and other local stressors through epigenetic mechanisms." (PMID 32118205, 2020). "For that purpose, lactate effects upon epigenetic enzymes, particularly SIRT1, and consequent alterations in tumor cell aggressiveness were firstly evaluated." (PMID 32340156, 2020). "SIRT1 is a protein deacetylase known to act as a tumor promoter or suppressor in different cancers 91-93." (PMID 33162823, 2020). "Tissue microarray analysis of HCC and adjacent nontumoral liver tissues revealed a positive correlation between the expression levels of SIRT1 and advancement of tumor grades." (PMID 32607257, 2020). "This is also one of the few studies with information on both MSI and CIMP CRC status as measured in tumour tissue, as well as information on germline SIRT1 genotype variation." (PMID 32098999, 2020). "For example, SIRT1 was shown by Rodgers and colleagues to promote tumor development by interfering with mitochondrial biosynthesis." (PMID 33585187, 2020). "Cells with SIRT1 overexpression showed increased sensitivity to cisplatin treatment, as indicated by reduced tumor sizes and increased TUNEL-labeled apoptotic cells." (PMID 32051395, 2020). "Other studies also reported that SIRT1 prevents tumor initiation through the promotion of telomere maintenance, the activity of homologous recombination and DNA repair." (PMID 32607257, 2020).
tumor (continued). "AMPK, autophagy, and SIRT1: The sensing capacity of growth signals and nutrient availability is essential to trigger adaptive metabolic responses favoring tumor growing." (PMID 31906264, 2020). "Among HDACs, SIRT1-5 accounted for deacetylation of non-histone proteins and several acetylated proteins identified in tumor tissues were substrates of SIRT1-5." (PMID 33093847, 2020). "We confirmed the overexpression of SIRT1 served as a tumor promoter gene by promoting the invasion, migration, and proliferation of PC-14/B cells but inhibited EMT." (PMID 32267139, 2020). "Sirt1 has been shown to have both tumor suppressor and tumor promoter properties depending on its deacetylation target." (PMID 32373350, 2020). "As members of the sirtuin family, SIRT1 AND SIRT3 have been shown to possess a tumor suppressor function (45, –, 50)." (PMID 31932479, 2020). "Numerous reports indicate melatonin’s stimulatory effect on SIRT1 expression in different types of non-tumor cells and tissues, including heart and kidneys." (PMID 33519498, 2020). "In summary, our results suggest that both activators and inhibitors of SirT1 have therapeutic potential as anti-tumor agents." (PMID 32366137, 2020). "Then we detected expression levels of SIRT1-5 in four pairs of tumor and normal liver tissues from HCC patients." (PMID 33093847, 2020). "For instance, RBP RPS3 was markedly up regulated in HCC tumor tissues and served as a critical tumor-promoting factor via up-regulating SIRT1." (PMID 33575212, 2020). "It has been reported that the miR-34a sensitized tumor cells to cisplatin by targeting SIRT-1 and CDK6." (PMID 33183321, 2020). "In support of this, recently, several studies reported a significant observation of Sirtuin1 (SIRT1) overexpression in the malignant tumor cells, including HCC." (PMID 32607257, 2020). "SIRT1 is an NAD+-dependent deacetylase that plays a crucial role in tumorigenesis through the deacetylation of tumor regulatory proteins." (PMID 32158616, 2020). "For a long time, SIRT1 was regarded as a tumor promotor due to its elevated activity in some kinds of cancers." (PMID 32486270, 2020). "Recent studies implicate the involvement of SIRT1 in tumor initiation, progression, and drug resistance by blocking senescence and apoptosis, as well as promotion of cell growth and angiogenesis." (PMID 33178616, 2020). "Sirt2, similarly to Sirt1, also has a regulatory function, and it has been suggested that it can act both as a tumor promoter and as a tumor suppressor." (PMID 33203121, 2020). "Doxorubicin and Trifolium pratense L. (Red clover) extract synergistically inhibited the metastasis of 4T1 to the lungs and brain by reducing cytokines (IL‐6 and IL‐8) and genes (SIRT‐1 and MMP‐2) associated with metastasis in tumor‐bearing BALB/c mice." (PMID 33133558, 2020). "In brief, SIRT4 exhibited a tumor-suppressor function in human neuroblastoma, and reduced the energy metabolism of tumor cells by inhibiting mitochondrial metabolism and SIRT1 expression." (PMID 33585187, 2020). "Several authors have highlighted a dual role of SIRT1 as both a tumor suppressor and a tumor promoter." (PMID 32806709, 2020). "Treatment with the Si-Sirt1 plus Adriamycin resulted in a significant reduction in tumor growth, compared with that of the Vector2 group via vivo imaging or macroscopic images." (PMID 32570218, 2020). "SIRT1 exerts a role in tumor initiation, progression, and angiogenic pathways, as depicted in murine hepatocellular carcinoma, highlighting the potential antitumoral role of this miRNA, through a SIRT pathway." (PMID 33123088, 2020). "Different studies have shown ambiguous implications of SIRT1 as both a tumor suppressor and tumor promoter." (PMID 31261609, 2019).
tumor (continued). "The major difference between non-tumor and tumor cells concerns the inverse relationship between melatonin and SIRT1 and the pro-apoptotic activity of melatonin in tumor cells." (PMID 30862067, 2019). "In contrast to these findings, SIRT1 was downregulated in OC based on public datasets and acts as a tumor suppressor." (PMID 31572453, 2019). "Several reports suggest that, SIRT1 deacetylate eNOS, stimulate its activity and enhance NO production and tumor angiogenesis." (PMID 32010617, 2019). "Our group has also reported that the horizontal transfer of miR-23a from tumor cell colonies can induces angiogenesis by targeting SIRT1 in the recipient endothelial cells." (PMID 32010617, 2019). "RT-PCR analysis demonstrated that, when compared with HP− tumor or normal tissue samples, the expression of miR-543 was significantly increased and SIRT1 expression decreased in HP+ tumor tissue." (PMID 31423013, 2019). "SIRT1 can modulate the activity of proteins important for oncogenesis and therefore, support tumor proliferation and progression as well as drug resistance." (PMID 31430957, 2019). "Recent studies have established that SIRT1 modulates tip and stalk behavior through deacetylation of intracellular domain (NICD) of NOTCH1 in tumor associated endothelial cells." (PMID 32010617, 2019). "SIRT1 overexpression in HCC samples correlated with advanced tumor stage and increased incidence of portal vein tumor thrombus." (PMID 31608282, 2019). "The deacetylation of many proteins involved in tumor suppressor processes or DNA damage repair, and the inactivation of specific pathways support the role of SIRT1 as a tumor promoter." (PMID 30761005, 2019). "Inhibition of NAMPT in ex vivo TANs followed by adoptive transfer of the TANs into tumor-bearing mice reduced tumor angiogenesis and proliferation through suppression of SIRT1 and resultant transcriptional blockade of pro-angiogenic genes." (PMID 32010616, 2019). "Biological studies revealed that these derivatives exert cytotoxicity via multiple mechanisms, such as by down-regulating a tumor-associated NADH oxidase (tNOX, ENOX2) and Sirtuin 1 (SIRT1)." (PMID 30909652, 2019). "SIRT1 overexpression correlated with smaller tumor size, while SIRT3 under-expression correlated with larger tumor size." (PMID 31139150, 2019). "In the tumor microenvironment, SIRT1 was engaged in the immune response through the activation of pro-inflammatory pathways." (PMID 31207928, 2019). "The two opposite functions of SIRT1 have been reported not only in tumor promotion and inhibition but also in tumor development." (PMID 31817470, 2019). "Sirt1 is downregulated in GBM tissues and cell lines, suggesting a tumor suppressor role of Sirt1 in GBM." (PMID 31319814, 2019). "In the current study, a significant rise in protein levels of sirtuin-1 was detected in the tumor cells of the mice treated with the monoclonal antibodies compared to non-treated animals." (PMID 31487876, 2019).
tumor (continued). "The influence of melatonin on SIRT1 expression has also revealed effects of either down- or upregulation, in this case, with a remarkable difference between tumor and non-tumor cells." (PMID 30862067, 2019). "Tumor suppression is associated with upregulation of SIRT1 levels, whereas SIRT3 and SIRT5 act differently as tumor promoters." (PMID 31137785, 2019). "In some cases, NAMPT was found to be a direct transcriptional target of c-Myc, resulting in a positive feedback loop between c-Myc, NAMPT, and SIRT1 that drove tumor cell proliferation and progression." (PMID 32010616, 2019). "SIRT1 also acts as a tumor suppressor via direct interaction with and consequent repression of other oncogenes, such as c-MYC." (PMID 30761005, 2019). "The expression level of SIRT1 is related to tumor stage, tumor invasion, lymph node metastasis, and shortened overall survival in patients with gastric carcinoma." (PMID 31817470, 2019). "In non-tumor cells, several effects of melatonin are abolished by inhibiting SIRT1, indicating mediation by SIRT1." (PMID 30862067, 2019). "Sirtuin 1 (SIRT1) is overexpressed in 55% of patients with HCC, which is associated with a higher tumor grade and poor long-term survival." (PMID 31430957, 2019). "Multiple studies have shown the process of SIRT1 being targeted by miR-22, miR-34a, miR-200a, miR-138, miR-30e-5P, miR-204, miR-212, and miR-449a to suppress cell proliferation in tumor progression." (PMID 31817470, 2019). "A total of 66 patients were enrolled, and the specimens of tumour tissues were collected before treatment to perform immunohistochemical (IHC) examinations and quantify the levels of SIRT1." (PMID 31684999, 2019). "The post-hoc analysis discerned 2 different SIRT1-H3k4ac/H3k9ac colocalization profiles depending on tumor subtype and 3 different colocalization profiles depending on gene type." (PMID 30093977, 2018). "A recent observation indicates that ROS accumulation in tumor cells can trigger down-regulation of SIRT1 to activate apoptosis." (PMID 29867453, 2018). "Overexpression of SIRT1 was reported to inhibit cell proliferation and tumor development through the mechanism of downregulation of NF-kB activity and inhibition of cyclin D1 signaling." (PMID 29991742, 2018). "ESRRA, NRF1, POLG, PPARGCA1 and SIRT1 were identified to be significantly down-regulated in all of the mtDNA-depleted tumours." (PMID 30208958, 2018). "In fact, numerous findings report a rise in SIRT1 activity in a diversity of cells and animal models after melatonin treatment, with the exception of some tumor cells, where the effect is inhibitory." (PMID 30029514, 2018). "It was revealed that miR-34a tumor-suppressive role is partly implemented by the means of suppressing SIRT1 expression in vitro." (PMID 30380732, 2018). "Our previous study has shown that SIRT1 is downregulated in GC and inhibits GC cell proliferation and xenografted tumor growth." (PMID 30250020, 2018). "The expression of several HDACs, including SIRT1, correlates to the G3 stage and, thus, to pNETs tumor grading." (PMID 30319549, 2018). "They showed that resveratrol inhibits AR–stimulated proliferation by activating SIRT1 in vitro, and that SIRT1 overexpression in xenograft model BALB/c mice represses tumor growth in vivo." (PMID 30380732, 2018). "As a result, the expression of SIRT1 was increased and p62 was decreased in the Comp 5-treated tumor tissues." (PMID 29991742, 2018). "The ambiguity surrounding the implications of SIRT1 in breast tumorigenesis stems from the discrepancy between studies, which have shown both tumor-suppressive and promoting functions of SIRT1." (PMID 30380732, 2018).